CACNA1I (calcium voltage-gated channel subunit alpha1 I)
Description:
Voltage-sensitive calcium channels (VSCC) mediate the entry of calcium ions into excitable cells and are also involved in a variety of calcium-dependent processes, including muscle contraction, hormone or neurotransmitter release, gene expression, cell motility, cell division and cell death. This channel gives rise to T-type calcium currents. T-type calcium channels belong to the 'low-voltage activated (LVA)' group and are strongly blocked by nickel and mibefradil. A particularity of this type of channels is an opening at quite negative potentials, and a voltage-dependent inactivation. T-type channels serve pacemaking functions in both central neurons and cardiac nodal cells and support calcium signaling in secretory cells and vascular smooth muscle. They may also be involved in the modulation of firing patterns of neurons which is important for information processing as well as in cell growth processes. Gates in voltage ranges similar to, but higher than alpha 1G or alpha 1H. [Isoform 3]: Voltage-sensitive calcium channels (VSCC) mediate the entry of calcium ions into excitable cells and are also involved in a variety of calcium-dependent processes, including muscle contraction, hormone or neurotransmitter release, gene expression, cell motility, cell division and cell death. This channel gives rise to T-type calcium currents. [Isoform 4]: Voltage-sensitive calcium channels (VSCC) mediate the entry of calcium ions into excitable cells and are also involved in a variety of calcium-dependent processes, including muscle contraction, hormone or neurotransmitter release, gene expression, cell motility, cell division and cell death. This channel gives rise to T-type calcium currents.
Synonyms: Ca(v)3.3; Cav3.3; NEDSIS
Tractability: Small molecule: an approved drug acts on it; a structure with a bound ligand is known; a high-quality ligand is known; it belongs to a druggable protein family. Antibody: its Gene Ontology location is reachable by antibodies, with high confidence; UniProt predicts a signal peptide or a membrane-spanning region; the Human Protein Atlas places it where antibodies can reach. PROTAC: a small molecule that binds it is known.
Target class: Voltage-gated calcium channel; Ion channel; Voltage-gated ion channel
Gene: Protein-coding gene on chromosome 22 (39,570,753 to 39,689,735, forward strand). Ensembl gene ENSG00000100346.
Subcellular location: Membrane
Subcellular location (Human Protein Atlas): Plasma membrane; Acrosome; Cell Junctions
Pathways (Reactome):
Developmental Biology: NCAM1 interactions
Muscle contraction: Smooth Muscle Contraction
Gene Ontology:
Molecular function: protein binding; voltage-gated calcium channel activity; high voltage-gated calcium channel activity; monoatomic ion channel activity
Biological process: calcium ion import across plasma membrane; signal transduction; calcium ion transmembrane transport; monoatomic ion transport; transmembrane transport
Cellular component: plasma membrane; voltage-gated calcium channel complex; membrane
Genetic constraint (gnomAD): Loss-of-function variants: 69 observed, 160.57 expected, observed/expected ratio (o/e) 0.43, 90% interval 0.35 to 0.52. The synonymous counts are far from expectation, so gnomAD's model fits this gene poorly and the ratio says little. Missense variants: 2,291 observed, 2,767.4 expected, observed/expected ratio (o/e) 0.83, 90% interval 0.8 to 0.86. Synonymous variants: 1,396 observed, 1,213.1 expected, observed/expected ratio (o/e) 1.15, 90% interval 1.1 to 1.2.
Homologues: Orthologues: chimpanzee CACNA1I (99% identical), macaque CACNA1I (93% identical), mouse Cacna1i (92% identical), rat Cacna1i (91% identical), pig CACNA1I (91% identical), guinea pig CACNA1I (88% identical), dog CACNA1I (85% identical), tropical clawed frog cacna1i (70% identical), zebrafish cacna1ia (63% identical), zebrafish cacna1ib (26% identical). Paralogues in human: CACNA1H (56% identical), CACNA1G (51% identical), CACNA1A (24% identical), CACNA1B (24% identical), CACNA1E (23% identical), CACNA1D (22% identical), CACNA1C (22% identical), CACNA1S (22% identical), CACNA1F (22% identical), SCN3A (20% identical), SCN8A (20% identical), SCN9A (20% identical), and 14 more.